PTBP3 (polypyrimidine tract binding protein 3)
Diseases named in the same sentence as PTBP3 in open-access papers (continued):
Sharing a sentence is not in itself a finding about the gene and the disease.
colon cancer (1 paper, 2019). "To detect the role of PTBP3 in colon cancer cells lung metastasis in vivo, we used tail vein injection mouse model." (PMID 31291975, 2019). "We also showed that PTBP3 also contributed the angiogenesis ability of colon cancer cells in vitro and in vivo." (PMID 31291975, 2019). "Our data showed that HIF-1α protein expression was significantly increased under normoxia and 1% O2 in PTBP3 OE colon cancer cell HCT116 and SW480." (PMID 31291975, 2019). "Enhanced PTBP3 expression promoted colon cancer cell proliferation, migration, and invasion in cultured cells, and also increased tumor growth and metastasis in animal model." (PMID 31291975, 2019). "To confirm effects on tumor growth in vivo, we performed xenograft model using nude mice to assess the effects of PTBP3 KD/OE on colon cancer cell growth." (PMID 31291975, 2019). "We also revealed that the blocking of HIF-1α pathway using HIF-1α inhibitor 2-MEOE2 can significantly reduce PTBP3 induced colon cancer cell migration and invasion in cultured cell lines, as well as tumor growth in animal xenografts model." (PMID 31291975, 2019). "To investigate whether PTBP3 contributes to aggressiveness of colon cancer, we first tested the effects of PTBP3 on cell migration and invasion in vitro, two critical features of the metastatic phenotype." (PMID 31291975, 2019). "To determine whether PTBP3 regulates cell viability in colon cancer cells, we measured cell viabilities using cell counting kit-8 (CCK8) in HCT116 cells with PTBP3 stable knockdown (KD) and overexpression (OE)." (PMID 31291975, 2019). "To further understand the biological function of PTBP3 in CRC processions, we investigated the malignant features of PTBP3 in colon cancer cell lines, HCT116, SW480 and SW620 using PTBP3 KD or OE lentivirus infection." (PMID 31291975, 2019). "To determine whether HIF-1α protein was regulated by PTBP3 in colon cancer, we detected the expression of HIF-1α in PTBP3 OE and KD colon cancer cells." (PMID 31291975, 2019). "Finally, we immunostained colon cancer TMAs for PTBP3 and HIF-1α to assess whether PTBP3 regulated HIF1a in human colon cancers, The results showed that PTBP3 expression strongly correlated with HIF-1α IHC scores in colon cancer tissues." (PMID 31291975, 2019).
endometrial carcinoma (1 paper, 2023). A malignant tumor arising from the epithelium that lines the cavity of the uterine body. "To verify whether SLC25A21-AS1 has clinical significance in other tumors, we performed TCGA analysis on more than 20 tumors and found that, in other gynecological tumors, such as Uterine Corpus Endometrial Carcinoma (UCEC), SLC25A21-AS1 expression was low, whereas PTBP3 expression was high." (PMID 36717926, 2023).
gallbladder cancer (1 paper, 2024). "To investigate the association between PTBP3 and clinical prognosis, we detected mRNA expression in 40 pairs of gallbladder cancer tissue samples using qPCR, and subsequently divided the samples equally into two groups based the logFold change values (low/high)." (PMID 39116343, 2024). "In conclusion, we found that expression of the splicing factor PTBP3 was significantly upregulated in gallbladder cancer and correlated with the prognosis of patients with gallbladder cancer." (PMID 39116343, 2024). "Together, our findings reveal that PTBP3 modulates exon skipping of IL‐18 to promote immune escape in gallbladder cancer, providing a new perspective for gallbladder cancer immunotherapy by blocking ΔIL‐18 production." (PMID 39116343, 2024). "Further, we found that PTBP3 promoted immune escape in gallbladder cancer via ΔIL‐18, which decreased FBXO38 transcription levels in CD8+T cells to reduce FBXO38‐mediated degradation of PD‐1." (PMID 39116343, 2024). "The in vivo experiment showed that PTBP3 knockdown significantly inhibited HuPBMC tumor growth and improved immunotherapeutic sensitivity in gallbladder cancer, as measured by subcutaneous tumor volume and mass." (PMID 39116343, 2024). "Based on the mRNA‐seq data from our 12 patients with gallbladder cancer, we used Spearman's analysis to explore the relationship between PTBP3 and immune cell infiltration." (PMID 39116343, 2024). "We found that PTBP3 promotes immune escape from gallbladder cancer through ΔIL‐18, both in vitro and in vivo." (PMID 39116343, 2024). "We decided to focus on PTBP3 because it was so markedly overexpressed, yet little is known about its function in gallbladder cancer." (PMID 39116343, 2024). "We also examined PTBP3 protein levels in the 12 pairs of gallbladder cancer and para‐cancerous tissues that we had previously used for mRNA sequencing." (PMID 39116343, 2024). "To investigate the role of PTBP3 in gallbladder carcinogenesis, we knocked down PTBP3 using siRNAs in two gallbladder cancer cell lines with high PTBP3 expression." (PMID 39116343, 2024). "In conclusion, our results show that PTBP3 promotes exon skipping of IL‐18 in gallbladder cancer." (PMID 39116343, 2024). "PTBP3 mediated IL‐18 exon skipping to promote immune escape from gallbladder cancer." (PMID 39116343, 2024). "Moreover, the PSI values of IL‐18 in the 12 gallbladder cancer samples were negatively correlated with the expression level of PTBP3 protein, consistent with the finding that PTBP3 promotes exon skipping of IL‐18." (PMID 39116343, 2024). "To investigate whether PTBP3 mediates gallbladder cancer immune escape via ΔIL‐18, we overexpressed PTBP3 in tumor cells and treated them with ASO4 to reduce ΔIL‐18 production." (PMID 39116343, 2024). "PTBP3 did not have a significant effect on the biological behavior of gallbladder cancer cells but facilitated immune escape of tumor cells by promoting exon skipping of IL‐18." (PMID 39116343, 2024). "Cell proliferation and transwell assays indicated that PTBP3 knockdown in gallbladder cancer cells did not significantly affect their proliferation, invasion, or migration ability." (PMID 39116343, 2024). "Taken together, PTBP3‐mediated pro‐tumorigenic effects are CD8+T cell‐dependent and ASO4 may have potential value in the treatment of gallbladder cancer." (PMID 39116343, 2024).
head and neck cancer (1 paper, 2025). A primary or metastatic malignant neoplasm affecting the head and neck. "CONCLUSIONS: We conclude that HIF1A-induced nuclear UCA1 stimulated cell migration and invasion via interacting with PTBP3, increasing lymph node metastasis in head and neck cancer." (PMID 41068676, 2025).
Hepatitis (1 paper, 2025). Inflammation of the liver. "The effects of the ER stress on the differentially expressed proteins Elovl5 and Ptbp3 during hepatitis were further demonstrated." (PMID 41209571, 2025).
kidney chromophobe (1 paper, 2022). "In contrast, PTBP3 showed lower expression in the tumours of kidney chromophobe (KICH), kidney renal clear cell carcinoma (KIRC), kidney renal papillary cell carcinoma (KIRP), and thyroid carcinoma (THCA) (all p < 0.05) relative to the corresponding adjacent normal tissues." (PMID 35359851, 2022).
liver disease (1 paper, 2025). "The rats' model of parenteral nutrition-associated liver disease was used to study changes in the ER stress markers, Elovl5 and Ptbp3, and their in vitro role was determined." (PMID 41209571, 2025). "We confirmed these findings in vitro by establishing that Elovl5 and Ptbp3 play a role in parenteral nutrition-related liver disease by modulating the ROS generation and cell death." (PMID 41209571, 2025).
metastatic cancer (1 paper, 2025). A carcinoma which has spread from the original site of growth to another anatomic site. "In conclusion, our study identifies PTBP3 as a key regulator of COX11 alternative splicing and highlights its role in the accumulation of shorter transcripts in metastatic cancer lesions." (PMID 40270362, 2025).
metastatic tumor (1 paper, 2025). "The results indicated that, compared to primary tumor tissues, the expression levels of PTBP3, RBFOX1, SRRM2, YBX3, and QKI were significantly higher in metastatic tumor tissues." (PMID 40270362, 2025).
prostate tumors (1 paper, 2019). "Microarray data obtained from GEO indicate that PTBP3 is upregulated in prostate tumors versus normal prostate tissue (GDS2545/35600; GDS4114/207223)." (PMID 30634466, 2019).
renal carcinoma (1 paper, 2024). A carcinoma arising from the epithelium of the renal parenchyma or the renal pelvis. "To investigate the possible molecular mechanism by which PTBP3 regulates renal cancer malignancy, we analyzed eCLIP-SEQ data on genome-wide PTBP3-RNA interactions in HCT116 cells." (PMID 38405614, 2024). "Overexpression of PTBP3 promotes renal cancer cell proliferation, migration, and invasion in vitro and increases tumor growth and metastasis in vivo." (PMID 38405614, 2024). "Additionally, PTBP3 promotes the migration and invasion abilities of renal cancer cells by regulating HMGA1 expression in vivo." (PMID 38405614, 2024). "In addition, PTBP3 promotes the proliferation and pulmonary metastasis of renal cancer cells in an animal xenograft model." (PMID 38405614, 2024). "Furthermore, PTBP3 promotes renal cancer cell proliferation, migration, and invasion in vitro as well as tumor growth and metastasis in vivo." (PMID 38405614, 2024). "PTBP3 promotes renal cancer cell growth and metastasis in vitro and in vivo." (PMID 38405614, 2024). "To investigate its role in RCC development, we assessed PTBP3 protein expression by IHC in patients with RCC using tissue microarray (TMA) slides, which contained 68 normal renal tissues and 302 renal cancer tissues." (PMID 38405614, 2024). "To determine the effect of PTBP3 on HMGA1 mRNA, we assessed the expression of HMGA1 in renal cancer cells with PTBP3 overexpression or knockdown." (PMID 38405614, 2024). "In the present study, PTBP3 promoted HMGA1 expression and renal cancer cell migration and invasion." (PMID 38405614, 2024).
renal cell carcinoma (1 paper, 2024). "IGF2BP3 silencing decreased HMGA1 protein levels accordingly in PTBP3 overexpressing renal cell carcinoma cells." (PMID 38405614, 2024). "HMGA1 overexpression restored the effect of PTBP3 downregulation on the proliferation, migration, and invasion of renal cell carcinoma in vivo." (PMID 38405614, 2024). "Our results demonstrate that PTBP3 promotes the growth and metastasis of renal cell carcinoma cells." (PMID 38405614, 2024). "Similarly, HMGA1 overexpression restored the effect of PTBP3 downregulation on proliferation and pulmonary metastasis of renal cell carcinoma cells in vitro." (PMID 38405614, 2024). "To determine whether PTBP3 regulates the activity of renal cell carcinoma cells, we measured the viability of stable knockdown (KD) and overexpression (OE) of PTBP3 in 786-O and ACHN cells using cell counting kit-8 (CCK8)." (PMID 38405614, 2024). "Our data demonstrated that PTBP3 promotes the proliferation of renal cell carcinoma cells." (PMID 38405614, 2024). "To investigate whether PTBP3 contributes to RCC invasiveness of renal cell carcinoma, we tested the effect of PTBP3 on cell migration and invasion in vitro, which are two key features of the metastatic phenotype." (PMID 38405614, 2024). "In this study, to determine the mechanism of PTBP3 in RCC, we investigated the expression of PTBP3 in clinical samples of patients with renal cell carcinoma, and analyzed its role and molecular mechanism in regulating the malignant characteristics of RCC." (PMID 38405614, 2024). "However, the molecular mechanisms of PTBP3 in renal cell carcinoma (RCC) remain unknown." (PMID 38405614, 2024). "However, the function and mechanism of action of PTBP3 in renal cell carcinoma remains unclear." (PMID 38405614, 2024).
sarcoma (1 paper, 2019). A usually aggressive malignant neoplasm of the soft tissue or bone. "YBX1 was reported could interact with HIF-1α 5’UTR to promote HIF-1α translation in sarcoma, we speculated that YBX1 may play as a cofactor of PTBP3 in regulating HIF-1α translation." (PMID 31291975, 2019).
Skin Cutaneous Melanoma (1 paper, 2022). "We further analysed the relationship between PTBP3 expression and tumour pathological staging and found stage-specific expressional changes in PTBP3 expression (e.g., ACC, KIRC, LIHC, Skin Cutaneous Melanoma (SKCM))." (PMID 35359851, 2022).
uterine tumours (1 paper, 2022). "This study indicated that the frequency of PTBP3 alteration (>4%) was the highest in uterine tumours with “mutation” as the primary type." (PMID 35359851, 2022). "The result found that the frequency of PTBP3 alteration (>4%) was the highest in uterine tumours with “mutation” as the primary type." (PMID 35359851, 2022).
ZIKV infection (1 paper, 2021). "We found that PTBP1, LIF, GHR, and PTBP3 were upregulated while EDNRB and MBP were downregulated upon ZIKV infection." (PMID 33891593, 2021). "Our results showed that mRNA levels of PTBP1, LIF, PTBP3, and GHR were significantly upregulated, while EDNRB and MBP were downregulated upon ZIKV infection at indicated time." (PMID 33891593, 2021). "Among the top selected differentially expressed genes, such as PTBP1, LIF, GHR, PTBP3, EDNRB, and MBP, the mRNA and protein expressions were confirmed to identify the dysregulation of the transcriptome in MPAs upon ZIKV infection." (PMID 33891593, 2021).
tumor (27 papers, 2014 to 2025). "Mice overexpressing PTBP3 exhibited weight loss due to aggressive tumor progression; however, this weight loss was alleviated after ASO treatment." (PMID 40270362, 2025). "In vivo experiments using the HuPBMC mouse model also confirmed that ASO4 reduced tumor progression caused by PTBP3 overexpression and showed significant anti‐tumor effects." (PMID 39116343, 2024). "Further analysis indicated that PTBP3 expression was positively correlated with the cancer-associated fibroblasts for most tumour types." (PMID 35359851, 2022). "In the immune infiltration analysis, we found that high PTBP3 expression was positively correlated with the cancer-associated fibroblast and neutrophil infiltration levels in most tumours, such as ACC, GBM, LIHC, and SARC." (PMID 35359851, 2022). "We also analysed the relationship between PTBP3 expression and tumour mutational burden (TMB) and microsatellite instability (MSI) in some tumours." (PMID 35359851, 2022). "We verified the association of the tumor size and PTBP3 with the metastasis of the lymph node through the univariate analysis." (PMID 32477006, 2020). "The tumourigenesis assay in female severe combined immune-deficient mice was used to confirm whether PTBP3 promoted tumour growth in vivo." (PMID 29752441, 2018). "The results demonstrated that overexpression of PTBP3 promoted tumor cell invasion and proliferation, while knockdown of PTBP3 inhibited tumor cell invasion and proliferation." (PMID 40270362, 2025). "Immunohistochemical staining revealed that PTBP3 was significantly upregulated in primary tumor tissues compared to adjacent normal tissues and exhibited significant overexpression in peritoneal metastatic lesions compared to primary tumors." (PMID 40270362, 2025). "These recovery experiments collectively demonstrated that alterations in the long and short COX11 transcripts, mediated by PTBP3, significantly influence the invasion and proliferation of tumor cells and organoids." (PMID 40270362, 2025). "Tumor cells were detected in both the peritoneum and abdominal organs, with the PTBP3 overexpression group exhibiting the highest number of tumor nodules." (PMID 40270362, 2025). "In this study, we analyzed single‐cell data and found that PTBP3 is overexpressed in GCPM tumor cells, correlating with poor patient outcomes." (PMID 40270362, 2025). "Overall, PTBP3‐mediated exon 4 skipping in COX11 pre‐mRNA is critical for tumor cell survival and progression in GCPM, offering potential therapeutic strategies targeting copper metabolism." (PMID 40270362, 2025). "In vivo experiments further demonstrated that PTBP3 promotes tumor growth and metastasis in the peritoneal cavity." (PMID 40270362, 2025). "Compared to the vector control group, PTBP3 overexpression significantly enhanced spheroid invasion potential, while PTBP3 knockout inhibited tumor cell invasion, as indicated by a reduction in spheroid diameter." (PMID 40270362, 2025). "Based on bioinformatics analysis and cell biology experimental validation, we demonstrated that PTBP3 was able to promote exon skipping of IL‐18, which generated ΔIL‐18, an isoform expressed only in tumor tissues." (PMID 39116343, 2024). "Compared to the control group, mice with xenografts of PTBP3 KD tumor cells formed smaller tumors in terms of tumor size and weight in vivo." (PMID 38405614, 2024). "Next, we constructed a HuPBMC mouse model to investigate the role of PTBP3 in the anti‐tumor function and immunotherapy sensitivity of CD8+T cells in gallbladder in vivo." (PMID 39116343, 2024). "To observe the effect of xenografts on tumor growth in vivo, we used a nude mouse model to evaluate the effect of 786-O PTBP3 KD cells and HMGA1 overexpression in 786-O PTBP3 KD cells on tumor growth." (PMID 38405614, 2024). "Based on these results, we used a tumor‐ and CD8+T‐cell co‐culture system to show that PTBP3 knockdown in tumor cells enhanced the anti‐tumor effects of CD8+T cells." (PMID 39116343, 2024).